IGF1 (insulin like growth factor 1)
Diseases named in the same sentence as IGF1 in open-access papers (continued):
Sharing a sentence is not in itself a finding about the gene and the disease.
breast cancer (continued). "In experiments EPL001 inhibits the proliferation in vitro of MCF7 breast cancer cells stimulated by IGF1 and causes a dose-dependent reduction in LH secretion by ovine pituitary cells in vitro and likewise reduces prolactin production." (PMID 29043108, 2017). "The mitogenic and antiapoptotic effects of IGF-1 are related to a poorer prognosis in breast cancer and increased all-cause mortality." (PMID 27562357, 2016). "Selected interactions of menopausal status and IGF1 pathway SNPs on breast cancer risk among European and East Asian women." (PMID 27376028, 2016). "In conclusion, our study observed associations between some IGF1 SNPs and breast cancer risk among European and East Asian women, although evidence of an association for other IGF pathway SNPs was limited." (PMID 27376028, 2016). "In our analyses of European and East Asian women, we observed associations between select IGF1 SNPs and breast cancer risk in both European and East Asian women." (PMID 27376028, 2016). "The protein encoded by IGF1 gene is similar to insulin, in function and structure and belong to a family of proteins involved in mediating growth and development of breast cancer." (PMID 27152840, 2016). "Consistent with this premise, risk for breast cancer is increased in association with higher circulating levels of insulin and IGF-1." (PMID 27338371, 2016). "Prospective studies performed by The Endogenous Hormones and Breast Cancer Collaborative Group39 have shown that women with the highest concentration of IGF1 have a 28% higher risk of developing breast cancer than women with the lowest concentration." (PMID 26983499, 2016). "Two SNPs of the IGF1 gene (rs1019731 and rs12821878) were associated with breast cancer risk among European women." (PMID 27376028, 2016). "Increased IGF1 levels would presumably lead to increased risk of breast cancer; however, our study found the opposite direction of effect." (PMID 27376028, 2016). "In Europeans, the minor alleles of two IGF1 SNPs (rs1019731 and rs12821878) were associated with reduced breast cancer risk." (PMID 27376028, 2016). "Several IGF1 polymorphisms were found to be associated with breast cancer risk and some of these associations were modified by menopausal status or breast tumor subtype." (PMID 27376028, 2016). "Only a small portion of this large risk is attributable to effects of treatment: lifestyle and genetic factors also need to be taken into account 84, and possibly the role of IGF‐1 in increasing breast cancer risk." (PMID 27734632, 2016). "The aim of this study was to investigate associations between IGF1 pathway single nucleotide polymorphisms (SNPs) and breast cancer risk among European and East Asian women, and potential interactions with menopausal status and breast tumor subtype." (PMID 27376028, 2016). "Stratified analyses of 1,037 cases and 1,050 controls from a population-based case–control study were conducted to assess associations with breast cancer for 22 SNPs across 5 IGF1 pathway genes in European and East Asian women." (PMID 27376028, 2016). "Several observational studies have suggested an association between IGF-1 level in circulation and a risk of some cancer, such as breast cancer and colorectal neoplasms." (PMID 27835910, 2016). "Epidemiological studies indicate that a high concentration of blood-circulating IGF-1 (endocrine fraction) is a risk factor in numerous types of cancer, including colon cancer, prostate cancer, breast cancer and non-small cell lung cancer." (PMID 25384883, 2015). "Increased serum levels of IGF-1 have been associated with a high risk of both prostate and breast cancer." (PMID 26225961, 2015). "Several epidemiologic studies reported a significant positive correlation between circulating IGF-1 and breast cancer risk, particularly among premenopausal women." (PMID 28480224, 2015).
breast cancer (continued). "In contrast, over the last two decades many studies have implicated the IGF-1 system in the development of several malignancies including breast cancer." (PMID 25743390, 2015). "Circulating IGF-1 levels play a significant role as a risk factor in the onset and development of mammary tumours in breast cancer." (PMID 25866791, 2015). "Total PCBs associated with AREG, CYP19A1, ESR2, FOS, KRAS and STC2 genes; PCB 126 associated with AREG, CYP19A1, and STC2 genes and PCB 15 associated with CYP19A1, EGFR, ESR2, FOS, and IGF1 genes overlapped with 17β-estradiol, breast cancer, and endometriosis." (PMID 26512648, 2015). "We also observed association of EGFR, FOS and IGF1 genes with EDCs, endometriosis and breast cancer." (PMID 26512648, 2015). "Our data demonstrate that insulin and IGF-1 can contribute to loss of nuclear MIER1α in the MCF7 breast carcinoma cell line." (PMID 26281834, 2015). "The IGF-1 signaling pathway activates several downstream signals important to breast cancer development and survival and has been also implicated in resistance to cytotoxic therapies." (PMID 25285159, 2014). "For example, elevated levels of insulin are associated with worse prognosis in breast cancer patients, and increased insulin-like growth factor-1 (IGF-1) levels are associated with an elevated risk of prostate and breast cancer." (PMID 24728273, 2014). "Evidence from clinical evaluation of systemic IGF-1 levels also reveals that IGF-1 plays a central role in breast cancer risk and outcome." (PMID 25062088, 2014). "Circulating levels of IGF-1 in adulthood are associated with height in men and inconsistently also in women and IGF-1 has consistently been associated with increased risk of cancer of the breast, prostate, and colorectum." (PMID 24173535, 2014). "Epidemiological studies have associated breast cancer development with increased IGF-1 serum levels." (PMID 24618835, 2014). "Our earlier studies demonstrated that IGF-1 increases the risk for breast cancer and contributes to poor outcome in cancer patients and pAkt is associated with poor clinical outcome in breast cancer patients." (PMID 25062088, 2014). "Previous studies from our group and others identified that women with increased serum or plasma IGF-1 levels had increased risk for breast cancer." (PMID 25062088, 2014). "Another theory involves adolescent growth, as childhood body fatness is associated with lower levels of insulin-like growth factor 1 and slower adolescent growth, a possible pathway to reduced breast cancer risk." (PMID 24443815, 2014). "IGF-1 levels have been associated with more aggressive breast cancers resulting in reduced disease free survival and reduced response to breast cancer treatment." (PMID 25062088, 2014). "In human malignancies, increased circulating IGF-1 was associated with a greater risk of several cancers, including breast cancer." (PMID 23663564, 2013). "The most significant correlation between increased levels of IGF-1 and the risk of cancer diagnosis was found for prostate cancer, pre-menopausal breast cancer, and colorectal cancer." (PMID 23525758, 2013). "IGF-1 is an essential growth factor for TEB formation that has been implicated in breast cancer progression." (PMID 24156623, 2013). "In the general population, higher circulating IGF1 levels are associated with increased incidence of prostate, colorectal, and premenopausal breast cancer." (PMID 23690770, 2013). "Insulin-like growth factor is produced by different cell types, and its role in cancer is well documented in prostate cancer, breast cancer, colorectal cancer and melanoma, where increased risks to these cancers were associated with higher IGF1 levels." (PMID 24237932, 2013). "High insulin-like growth factor-1 concentrations are linked to both larger breast volume and increased risk of premenopausal breast cancer." (PMID 24349006, 2013).
breast cancer (continued). "Elevated circulating IGF-1 levels have been significantly associated with an increased risk of breast cancer, while the evidence for IGF-2 is less clear." (PMID 22662119, 2012). "Evidence from epidemiologic studies as well as animal studies suggests that elevated IGF-1 levels increase the risk of mammary tumors." (PMID 22414675, 2012). "The major up-regulated canonical pathways were identified as all being classically associated with cell signaling including PI3K/AKT/p70S6 and IGF1 all of which have been associated with poor prognosis in previous studies of ER+ breast cancer." (PMID 22608253, 2012). "In the 40% CR and 40% CR + IGF-1 comparison, at least two functional categories highly relevant for the effects of obesity on breast cancer risk were identified: maturity onset of diabetes and PPAR signaling pathway." (PMID 23342276, 2012). "Obese women, who are at higher risk to get breast cancer postmenopausally, also have higher IGF-1 blood levels." (PMID 23320178, 2012). "The resulting GH/IGF-1 excess in these animals is potentially important in the enhanced breast cancer progression associated with this model." (PMID 22174695, 2011). "Circulating levels of IGF-1 are positively associated with increased breast cancer risk in pre- and postmenopausal women, particularly for estrogen-receptor positive tumors." (PMID 21888628, 2011). "Here we demonstrate that IGF-1 plays a role in the activation of MMPs and causes increased invasive potential in breast cancer cells." (PMID 21535875, 2011). "Insulin like growth factor-1 (Igf-1) signaling promotes proliferation and inhibits apoptosis of breast cancer cells, and high plasma levels of Igf-1 are associated with risk of breast, prostate and other cancers." (PMID 21589862, 2011). "Human candidate-gene association studies that have tested IGF1 locus polymorphisms reported mixed results ranging from significant low-penetrance to null associations between IGF1 alleles and breast cancer risk." (PMID 21625632, 2011). "Herein we have shown that there is a causative mechanism of the IGF-1/IGF-1R axis in the antiestrogen drug resistance of breast cancer cells." (PMID 21595894, 2011). "Researchers in two prior studies observed that the risk of breast cancer was highest among women with high levels of both IGF-1 and at least one sex hormone (for example, testosterone or estradiol)." (PMID 22017816, 2011). "In vitro animal models showed IGF-1 to be a significant risk factor in mammary tumor onset and development." (PMID 21773024, 2011). "Of particular interest, IGF-1 protein has been most strongly implicated in breast cancer progression because of its mitogenic and anti-apoptotic effect on mammary epithelial cells." (PMID 21535875, 2011). "As with breast cancer, the underlying factors appear to be elevated glucose, insulin and IGF-1 levels." (PMID 21773024, 2011). "Increased IGF1 levels have been associated with breast cancer and increased breast cancer susceptibility." (PMID 21625632, 2011). "It seems that, at least in the current dataset, the IGFBP3 measures do not add substantial information in assessing the relationship of IGF1 with breast-cancer risk." (PMID 20472501, 2010). "The results of this collaborative analysis show that plasma concentrations of IGF1 are positively associated with breast-cancer risk." (PMID 20472501, 2010). "In human population studies, higher IGF-1 levels in the circulation are associated with some cancer types, including colorectal, prostate, and breast cancers." (PMID 23675206, 2010). "The incidence of breast cancer has been associated with levels of IGF1 and IGFBP3 in premenopausal women in most, but not all studies." (PMID 20302654, 2010). "The associations of IGF1 with height, age at menarche, age at first full-term pregnancy, and time since menopause are compatible with the possibility that these factors affect breast-cancer risk partly through their relationships with IGF1." (PMID 20472501, 2010).
breast cancer (continued). "The association of IGF1 with breast-cancer risk was confined to oestrogen-receptor-positive tumours." (PMID 20472501, 2010). "Variation in IGFBP3 concentrations by breast-cancer risk factors was less pronounced than that for IGF1 (webappendix p 2)." (PMID 20472501, 2010). "This collaborative analysis has confirmed a positive association between IGF1 and breast cancer risk." (PMID 20472501, 2010). "The relationship of IGF1 with breast-cancer risk for postmenopausal women was examined together with the associations with oestradiol and testosterone." (PMID 20472501, 2010). "The odds ratios (ORs) with 95% CIs of breast cancer associated with increasing IGF1 concentrations were estimated by conditional logistic regression in 4790 cases and 9428 matched controls, with stratification by study, age at baseline, and date of baseline." (PMID 20472501, 2010). "Separately, the SNPs comprising this haplotype have been reported to be associated with IGF1 levels and breast cancer risk." (PMID 20302654, 2010). "Plasma concentrations of IGF1 are influenced by nutritional factors such as energy and protein intake, and the possibility of lowering breast-cancer risk by reducing IGF1 should be explored." (PMID 20472501, 2010). "IGFBP3 was positively associated with breast-cancer risk, but this association was weak, and was eliminated by adjustment for IGF1, suggesting that the association of IGFBP3 with risk is due to its positive correlation with IGF1." (PMID 20472501, 2010). "The polymorphism rs6220 has also been correlated with elevated IGF1 levels whereas homozygosity G/G of rs2162679, has been associated with reduced breast cancer risk as well as reduced levels of IGFBP3." (PMID 20302654, 2010). "By contrast, adjustment of the association between IGFBP3 and breast-cancer risk for IGF1 reduced the OR for linear trend from 1·12 (95% CI 1·00–1·26) to 0·99 (0·87–1·14)." (PMID 20472501, 2010). "The associations of IGF1 with risk factors for breast cancer in controls were examined by calculating geometric mean concentrations in categories of these factors." (PMID 20472501, 2010). "Women in the highest fifth of IGF1 had a 28% higher risk of breast cancer than women in the lowest fifth." (PMID 20472501, 2010). "Nevertheless, one study reported an increased risk of breast cancer with increasing IGF1 levels also for postmenopausal HT-users (>55 years)." (PMID 20302654, 2010). "The type I insulin-like growth factor receptor (IGF1R) is overexpressed by many breast cancer cell lines and high levels of IGF1 are associated with poor prognosis in breast cancer." (PMID 19536088, 2009). "Western blot analysis of MCF-7 human breast carcinoma cells in culture showed that 2 h pretreatment of auraptene (10 μM) resulted in nearly a total loss of IGF-1 induced cyclin D1 expression at 8 h." (PMID 19640308, 2009). "We interpret our findings as indicating that higher levels of pregnancy hormones and growth hormones during the immediate postnatal period, particularly IGF-1, play an important role in premenopausal breast cancer risk several decades later." (PMID 18827810, 2008). "The protective effect of increasing parity on breast cancer risk in the developed world is thought to be mediated in part by decreasing circulating IGF-1 levels." (PMID 17311016, 2007). "Our findings suggest that the combination of IGF1-19/-19 genotype and multiparity is associated with an early age at breast cancer diagnosis." (PMID 17311016, 2007). "Conversely, in China, where it is uncommon to have more than one child, the IGF1-19/-19 genotype was associated with a decreased risk of early onset breast cancer." (PMID 17311016, 2007). "Early-onset breast cancer (<50 years) has been associated with high insulin-like growth factor-1 (IGF-1) levels." (PMID 17311016, 2007).
breast cancer (continued). "Other biological mechanisms have also been proposed to explain the observed protective effect of preeclampsia, including immunological factors and alterations in IGF-1 and other compounds linked to breast cancer initiation and promotion." (PMID 17687337, 2007). "In the IGF1 gene, we noted an association of the rs2162679 SNP, with the G/G genotype being associated with a reduction in risk of breast cancer (P=0.05) and also a modest effect in the heterozygote (P-trend for codominant model=0.03)." (PMID 16404426, 2006). "Parous women in the general population have lower IGF-1 levels than nulliparous women; after pregnancy, the risk of breast cancer is transiently increased, and is then lower for a period extending into the postmenopausal years." (PMID 15756256, 2005). "High IGF-1 levels are linked to early-onset breast cancer and larger breast volumes in the general population." (PMID 15756256, 2005). "The insulin-like growth factor 1 (IGF1) protein has been implicated in breast cancer because of its mitogenic and antiapoptotic effect on mammary epithelial cells." (PMID 12610514, 2003). "The insulin-like growth factor 1 gene (IGF1) is a strong candidate gene for a breast cancer susceptibility model." (PMID 12610514, 2003). "We investigated a dinucleotide repeat 969 bp upstream from the transcription start site of the IGF1 gene for possible associations with plasma IGF1 levels and breast cancer risk in a multiethnic group of postmenopausal women." (PMID 12610514, 2003). "Higher IGF-1 and IGFBP-3 levels in CC genotype carriers could indicate enhanced tumorigenic pathways mediated through IGF signalling, potentially influencing breast cancer susceptibility and progression." (PMID 40493660, 2025). "Importantly, dysregulation of the IGF-1/IGF-1R axis has been increasingly implicated in therapy resistance in breast cancer." (PMID 41157306, 2025). "IGF-1 and its binding proteins and receptors play critical roles in human tissue development, particularly in the mammary gland, where dysregulation can increase breast cancer risk and accelerate its progression." (PMID 40493660, 2025). "The observed association between the IGFBP-3 A-202C polymorphism and breast cancer risk may be explained through its role in regulating IGF-1 bioavailability and apoptosis." (PMID 40493660, 2025). "Similarly, analyses from the UK Biobank demonstrated that higher IGF-1 was associated with increased risks for multiple cancers, including breast cancer (HR = 1.10; 95% CI, 1.07–1.14)." (PMID 41293738, 2025). "By synthesizing these data, our objective was to clarify whether prolonged exposure to GH and IGF-1 excess is associated with an increased risk of breast cancer in patients with acromegaly." (PMID 41293738, 2025). "High levels of IGF1 are associated with an increased risk of breast cancer, suggesting that an early decrease in IGF1 levels may contribute to the protective effect of pregnancy." (PMID 40243654, 2025). "Evidence regarding IGFBP-3 gene polymorphisms’ implications in serum levels of IGFBP-3 and IGF-1 in the Gaza Strip and their association with breast cancer risk remains unclear." (PMID 40493660, 2025). "Consistent with these mechanistic insights, early clinical reports suggested up to a four-fold increase in breast cancer risk among women with acromegaly and more recent studies have demonstrated a positive association between cumulative GH/IGF-1 exposure and breast cancer incidence." (PMID 41293738, 2025). "This study examined the impact of insulin-like growth factor binding protein-3 (IGFBP-3) A-202C polymorphism (rs2854744) on breast cancer risk and its association with insulin-like growth factor-1 (IGF-1) and IGFBP-3 serum levels among Palestinian women in the Gaza Strip." (PMID 40493660, 2025).